KIF5A (kinesin family member 5A)
Diseases named in the same sentence as KIF5A in open-access papers (continued):
Sharing a sentence is not in itself a finding about the gene and the disease.
Alzheimer disease (3 papers, 2022 to 2023). A progressive, neurodegenerative disease characterized by loss of function and death of nerve cells in several areas of the brain leading to loss of cognitive function such as memory and language. "Changes in KIF5A expression have been inconsistently linked to Alzheimer’s disease." (PMID 35750148, 2022). "Seven of these genes are Alzheimer’s disease-related, six are down-regulated with both Apoer2-ICDs (COX7A2L, FZD2, KIF5A, MAP2K2, PSENEN, RAF1) and one with only the Apoer2-ICD[Δ19] (SLC39A9)." (PMID 37461529, 2023).
bladder cancer (3 papers, 2021 to 2025). "have proved that KIF5A can regulate the bladder cancer development and progression." (PMID 35141153, 2021).
hepatocellular carcinoma (3 papers, 2022 to 2024). A malignant tumor that arises from hepatocytes. "who found that KIF5A was abnormally upregulated in hepatocellular carcinoma (LIHC), and its high expression level may be positively correlated with the malignant phenotype of LIHC, suggesting that KIF5A may be associated with LIHC disease progression." (PMID 39517115, 2024).
motor neuron diseases (3 papers, 2011 to 2026). "KIF5A encodes for a neuronally enriched kinesin involved in protein transport, and mutations within this gene have been causally linked to different motor neuron diseases." (PMID 40555518, 2025). "Interaction of ZFYVE27 with spastin, VAP-A/B and KIF5A highlights its role in motor neuron disease." (PMID 22216323, 2011). "Our findings suggest that SMN-independent interventions targeting KIF5A could represent a complementary therapeutic approach for SMA and other motor neuron diseases." (PMID 41885937, 2026).
Autosomal dominant spastic paraplegia type 10 (2 papers, 2019 to 2024). "KIF5A is predicted to be the most disease relevant seed gene (raw score 0.2954; normalized score 0.033) because it maps to spastic paraplegia 10 in OMIM (OMIM 604187) and DISGENET (C1858712)." (PMID 31404076, 2019).
axonal neuropathy (2 papers, 2015 to 2018). Any nerve disorder affecting the axon of a nerve. "Mutations in KIF5A are described in a wide clinical spectrum from hereditary spastic paraplegia (HSP) 10 to axonal neuropathy and was recently implied in early-onset phenotype with severe myoclonus and evidence of mitochondrial dysfunction." (PMID 29625556, 2018). "Interestingly, mutations in KIF5A, a gene encoding the neuronal kinesin heavy chain implicated in anterograde axonal transport, have been associated with “pure” HSP, although a fraction of family members shows electrophysiological evidence of sensory-motor peripheral axonal neuropathy." (PMID 26517984, 2015).
epilepsy (2 papers, 2013 to 2020). A brain disorder characterized by episodes of abnormally increased neuronal discharge resulting in transient episodes of sensory or motor neurological dysfunction, or psychic dysfunction. "Kinesin family member 5A (KIF5A) has been reported to regulate neuronal surface expression of GABA(A)Rs via an interaction with GABA(A)R-associated protein (GABARAP), indicating that KIF5A could be involved in inhibitory neural transmission regulation related to epilepsy." (PMID 33718116, 2020).
glioma (2 papers, 2023 to 2024). A benign or malignant brain and spinal cord tumor that arises from glial cells (astrocytes, oligodendrocytes, ependymal cells). "In contrast, KIF5A and EHD2 displayed differential expression between GBM and all other gliomas." (PMID 38638676, 2024).
lung adenocarcinoma (2 papers, 2022 to 2024). A carcinoma that arises from the lung and is characterized by the presence of malignant glandular epithelial cells. "The aim of this study was to investigate the effect of KIF5A on lung adenocarcinoma (LUAD) and its potential molecular mechanisms." (PMID 39517115, 2024). "Kinesin family member 5A (KIF5A) inhibits lung adenocarcinoma (LUAD) cell anoikis, while the small molecule drug Ergotamine targets and inhibits the expression of KIF5A, which in turn induces LUAD cell anoikis." (PMID 39517115, 2024). "Moreover, KIF5A mRNA levels were negatively correlated with miR-103a and positively correlated with ZEB1 in KP cells and in The Cancer Genome Atlas lung adenocarcinoma cohort." (PMID 34874914, 2022).
motor neuron degeneration (2 papers, 2023 to 2024). "KIF5A plays a pivotal role in axonal transport, shedding light on the possibility that mutations in KIF5A can disrupt this process, thus contributing to the development of motor neuron degeneration." (PMID 38028604, 2023). "Despite all these similarities, the N999Vfs*40 and C975Vfs*73 KIF5A mutants lead to strikingly different neurological conditions, respectively an adult-onset form of motor neuron degeneration and a complex and very severe early-onset neurodevelopmental phenotype." (PMID 39333504, 2024).
neuropathy (2 papers, 2012 to 2021). A disorder affecting the nervous system that manifests with pain, tingling, numbness, and/or muscle weakness. "Mutations in the gene for the KIF5A subunit of kinesin 1 (formerly SPG10) are associated with an early-onset, pure form of HSP, exhibiting a dying-back neuropathy characterized by progressive weakness and spasticity of the legs." (PMID 22312314, 2012).
rheumatoid arthritis (2 papers, 2010 to 2014). A chronic, systemic autoimmune disorder characterized by inflammation in the synovial membranes and articular surfaces. "For example, a variant in kif5a locus has been linked with the risk to develop rheumatoid arthritis and is a candidate SNP in MS." (PMID 25274010, 2014).
autoimmune disease (1 paper, 2012). A disorder resulting from loss of function or tissue destruction of an organ or multiple organs, arising from humoral or cellular immune responses of the individual to their own tissue constituents. "Taken together, our results nevertheless provide mechanistic insight into how polymorphism in other kinesins including KIF21B and KIF5A influence human autoimmune disease susceptibility." (PMID 23300462, 2012). "Kinesin family members are involved in the activation of immune cells and inflammatory responses, and autoimmune disease GWAS identified KIF21B and KIF5A as candidates for autoimmune disease genes, suggesting an immunoregulatory role for kinesin family members." (PMID 23300462, 2012).
depression (1 paper, 2025). "This study provides novel insights into the molecular mechanisms of antidepressant effects of baicalin, highlighting KIF5A as a potential therapeutic target for depression." (PMID 40290440, 2025).
diabetes (1 paper, 2018). "Specifically, we showed that short-term diabetes alters both the mRNA levels and axoplasm content of KIF1A and KIF5B and axoplasm content of KIF5A and Myosin Va, but only in male animals." (PMID 29351809, 2018). "We show that short-term diabetes alters mRNA levels and axoplasm protein contents of kinesin family member KIF1A, KIF5B, KIF5A and Myosin Va in male but not in female rats." (PMID 29351809, 2018).
glaucoma (1 paper, 2022). Increased pressure in the eyeball due to obstruction of the outflow of aqueous humor. "In particular, stress granules have been implicated in at least one form of glaucoma, which combined with our data suggests exploring the role of both stress granules and mitochondria as disease-relevant Kif5a cargo as an exciting future direction." (PMID 35259089, 2022). "We also explored changes in Kif5a synthesis after axon injury expanding our investigation to another optic neuropathy, the circumlimbal suture model of glaucoma." (PMID 35259089, 2022). "Among these, Kif5a showed decreased synthesis when normalized to the total newly synthesized proteome after induction of glaucoma, while Kif5b was relatively unchanged (complete data in)." (PMID 35259089, 2022). "Although overexpression of Kif5a did not increase RGC survival after injury, the conservation of RGC-enriched Kif5a expression across species suggests a strategy of manipulating Kif5a therapeutically to restore axonal transport after injury or in neurodegenerative diseases like glaucoma." (PMID 35259089, 2022).
glioblastoma (1 paper, 2024). The most malignant astrocytic tumor (WHO grade IV). "The mRNA expression of EPS15 and KIF5A was significantly downregulated in both the TCGA and REMBRANDT glioblastoma datasets, and EHD2 was upregulated in both datasets." (PMID 38638676, 2024).
hematoma (1 paper, 2021). A hematoma is a collection of blood from a vascular structure into an extravascular space. "This suggests that, aside from the KIF5A+ neuronal cell cluster, most cells in hematoma effluent are peripheral in origin." (PMID 33749664, 2021).
juvenile idiopathic arthritis (1 paper, 2025). Juvenile idiopathic arthritis (JIA) is the term used to describe a group of inflammatory articular disorders of unknown cause that begin before the age of 16 and last over 6 weeks. "Other loci, including STAT4, tnf receptor associated factor 1(TRAF1)/C5, Chr6q23, kinesin family member 5A (KIF5A), and protein kinase C theta (PRKCQ)are involved in juvenile idiopathic arthritis." (PMID 40236704, 2025).
neonatal intractable myoclonus (1 paper, 2024). "Frameshift mutations targeting the KIF5A tail are instead linked to ALS (MIM#617921) and to a complex infantile neurodevelopmental disorder with leukoencephalopathy named neonatal intractable myoclonus (NEIMY, MIM#617235)." (PMID 39333504, 2024).
optic neuritis (1 paper, 2018). Optic neuritis is inflammation of the optic nerve, the nerve that carries the visual signal from the eye to the brain.The conditionmay cause sudden, reduced vision in the affected eye(s). "A previous study reported axonal transport deficits at the onset of optic neuritis in EAE mice, whereas reduced levels of the axonal motor protein KIF5A (kinesin heavy chain isoform 5A) were found in MS patients." (PMID 30542317, 2018).
Optic neuropathy (1 paper, 2022). "Although here we describe initial data on the axon transportome cargoes dependent on Kif5a for their RGC axon localization, we do not yet understand which cargoes of Kif5a contribute to optic neuropathy, especially in vivo." (PMID 35259089, 2022).
osteosarcoma (1 paper, 2009). A usually aggressive malignant bone-forming mesenchymal neoplasm, predominantly affecting adolescents and young adults. "First, we examined the mRNA expression levels of KIF5B in three cancer cell lines(MCF-7, HeLa and U2OS osteosarcoma) and found it to be highly expressed in allthree cell lines when compared to other N-kinesins including KIF5A/KIF5C(Kinesin 1), KIF3A (Kinesin 2) and KIF1A (Kinesin 3)." (PMID 19242560, 2009).
primary progressive MS (1 paper, 2021). "For example, SPG2 has been shown to mimic MS, and rare variants in genes including KIF5A and REEP1 were identified in patients with primary progressive MS." (PMID 33646413, 2021).
respiratory failure (1 paper, 2020). The significant impairment of gas exchange within the lungs resulting in hypoxia, hypercarbia, or both, to the extent that organ tissue perfusion is severely compromised. "Also relevant to this discussion are the observations that mice with KO of genes encoding KIF1Bβ and KIF5A die from respiratory failure after birth." (PMID 32553155, 2020).
viral infection (1 paper, 2021). "The most down-modulated genes were related to T helper 2 pathway activation and induction of FOXP3 expression (AREG), immune tolerance (SMAD6), response to bacterial and viral infection and inflammation (CXCL8, PDE12, STX19, DFNB31), cell transport of glucose and organelles (KIF5A, SCL2A7)." (PMID 35058920, 2021).
tumor (10 papers, 2021 to 2024). "Based on CAMOIP database, we further explored the association between KIF5A expression with anti-tumor immune response." (PMID 36686769, 2022). "In addition, exome sequencing for 64 tumor samples from 55 PCa patients demonstrated that the KIF5A mutation was related to aggressive diseases." (PMID 36675580, 2023). "A tumour with the KIF5A::NTRK2 fusion that developed in the right lateral and 3rd ventricles of patient #2 (15 y/F) exhibited features of a LG MGNT." (PMID 39014476, 2024). "CCK‐8 was carried out to determine the viability of suspended NCI‐H2087 cells in different groups, revealing that knocking down KIF5A strikingly dampened the vitality of tumor cells." (PMID 39517115, 2024). "Next, we measured the differential expression of KIF5A in LUAD tumor tissues and adjacent normal tissues, finding that the expression of KIF5A was considerably upregulated in LUAD tissues." (PMID 39517115, 2024). "Above results highlighted the latent functions of KIF5A in tumor immune response and TME, rendering us to deeply explore its biological role in subsequent analyses." (PMID 36686769, 2022). "KIF5A expression was investigated across tumor types in the TCGA database using paired differential analyses." (PMID 36686769, 2022). "LINC00449 has the potential to serve as a biomarker for HCC and may mediate tumor progression through the LINC00449/miR-329-3p/KIF5A regulatory network." (PMID 39632786, 2024). "Above results suggested that for patients with high-level of KIF5A, although they had relatively worse prognosis, they might have a chance to elicit stronger anti-tumor response and get benefit from immunotherapy." (PMID 36686769, 2022). "According to these results, we can infer that KIF5A could also be an innovative biomarker reflecting unique tumor microenvironment of LIHC and need further exploration." (PMID 36686769, 2022). "Using bioinformatics analysis methods and molecular experiments, the expression of KIF5A in LUAD was analyzed, with its expression in attached and detached tumor cells assessed." (PMID 39517115, 2024). "In this study, we demonstrated that KIF5A was highly upregulated in LUAD, exhibiting the inhibiting impact on LUAD cells as well as the promoting impact on tumor cell proliferation." (PMID 39517115, 2024). "Notably, our qRT-PCR result showed that the expression of KIF5A is downregulated in PCa cells compared to normal prostate epithelial cells, which is contrary to the result of the TCGA database and may be related to tumor heterogeneity." (PMID 36675580, 2023). "We figure out latent biological function of KIF5A and its important role in LIHC tumor microenvironment." (PMID 36686769, 2022). "There was a strong negative correlation between KIF5A mRNA expression and tumour grade, and a strong positive correlation between EHD2 expression and grade." (PMID 38638676, 2024). "We constructed a novel seven-gene signature (B3GALT5-AS1, DNER, CSN1S1, KIF5A, SIX3, NOTUM, and CPS1) and a combined prognostic model integrating a seven-gene signature with patient age and tumor size to quantify the likelihood of distant metastasis in lymph node-negative TNBC." (PMID 34604089, 2021). "Furthermore, immune infiltration and immune function analyses revealed upregulated KIF5A could predict a unique tumor microenvironment with more CD8+T cells and a higher level of anti-tumor immune response." (PMID 36686769, 2022). "Specifically, although high expression of KIF5A in LUAD promotes cancer progression, inhibits anoikis, under Ergotamine treatment, the expression of the pro‐cancer gene KIF5A is suppressed, leading to anoikis of the cells, which may play a certain anti‐tumor role." (PMID 39517115, 2024).
cancer (7 papers, 2009 to 2025). A tumor composed of atypical neoplastic, often pleomorphic cells that invade other tissues. "Notably, KIF5A, however, is also tightly linked to the occurrence and progression of various human cancers." (PMID 39517115, 2024). "Expression analyses in pan-cancer revealed that KIF5A was abnormally expressed in various cancers, including LIHC." (PMID 36686769, 2022). "In addition, most proteins in the kinesin superfamily, including KIF5A, have been proven to reinforce cancer cell metastasis." (PMID 39517115, 2024). "Kinesin family member 5A (KIF5A) has been reported to be closely related to cancer progression." (PMID 39517115, 2024). "All these results proposed that KIF5A might be a potential target for anti-cancer strategies for LIHC." (PMID 36686769, 2022). "Taken together, KIF5A might serve as a novel prognostic biomarker for predicting immunotherapy response and could be a potential target for anti-cancer strategies for LIHC." (PMID 36686769, 2022). "The data presented here suggest that KIF5B is implicated in several pathwaysinvolving lysosomes and that its highly expressed in all cancer cell lines tested,as compared to other N-Kinesins including KIF5A/KIF5C (Kinesin 1 family), KIF3A(Kinesin 2 family) and KIF1A (Kinesin 3 family)." (PMID 19242560, 2009). "As one of the members of the kinesin superfamily, KIF5A may also be related to cancer progression." (PMID 39517115, 2024). "Although we identified the requirement of KIF11 for the transport of β-actin mRNP in fibroblasts and carcinoma cells, KIF5A was not shown to be involved in this cellular process." (PMID 25588836, 2015). "Genes such as KIF5A, SOX10, MYL9, TRIM9, MYH11, and SNAP25 are known to play important roles in biological development, suggesting that LRP1B may also be a key factor in cancer." (PMID 40170839, 2025). "The observed invasiveness was not seen in the cells that expressed the KIF5A tail (806–1032), suggesting the importance of endogenous communication of ZBP1 and KIF11 in the invasiveness of cancer cells." (PMID 25588836, 2015).
neurodegenerative disease (7 papers, 2006 to 2024). A disorder of the central nervous system characterized by gradual and progressive loss of neural tissue and neurologic function. "Indeed, mitochondrial dysfunction has been associated with several neurodegenerative diseases, including KIF5A-related conditions." (PMID 39333504, 2024). "In recent years, mutations in Kif5a have been implicated in neurodegenerative diseases including Charcot-Marie-Tooth and ALS40–42; however, the exact mechanism of how Kif5a mutations cause these diseases remains unclear." (PMID 36862119, 2023). "A mutation in KIF5A could result in the accumulation of neurofilaments and hinder the transport of mitochondria, potentially serving as a hallmark of neurodegenerative diseases." (PMID 38028604, 2023). "Discussion: We concluded our study by finding a crucial variant of KIF5A and its potential therapeutic target (epigallocatechin gallate) and KIF5A associated significant genes with important regulators which could decrypt the novel therapeutics in ALS and other neurodegenerative diseases." (PMID 38028604, 2023).
neurological disorders (7 papers, 2016 to 2026). "Specifically, mutations in the Kif5A gene, a closely related kinesin, are causes of various neurological disorders including Charcot-Marie Tooth and ALS." (PMID 36672174, 2023). "Disturbance in KIF5A gene expression in an Aβ-dependent or independent manner impairs the axonal anterograde/retrograde transport which increases its specificity for subsequent neurological disease-associated abnormal behavior and mortality." (PMID 35958988, 2022). "Mutations in KIF1A (resulting in KIF1-associated neurological disorder/KAND), KIF1B (resulting in Charcot-Marie-Tooth disease), KIF5A (resulting in ALS), and KIF21B (causing neurodevelopmental disorders) result in various neurological disorders where intracellular transport defects are evident." (PMID 41277110, 2026).
peripheral neuropathy (4 papers, 2015 to 2022). A disorder affecting the peripheral nervous system. "In the context of disease, several pathogenic variants in KIF5A are associated with a disease spectrum ranging from upper motor neuron involvement to peripheral neuropathy." (PMID 33810506, 2021). "When presenting as peripheral neuropathy, KIF5A-related disease is characterized by axonal sensorimotor neuropathy, but can variably include central nervous system involvement." (PMID 33810506, 2021).